MKI67 (marker of proliferation Ki-67)
Diseases named in the same sentence as MKI67 in open-access papers (continued):
Sharing a sentence is not in itself a finding about the gene and the disease.
brucellosis (1 paper, 2024). Brucellosis is a bacterial infection that spreads from animals to people via unpasteurized dairy products or by exposure to contaminated animal products or infected animals. "Plasmablast B cells (B_Plasmablast) displayed high MKI67 and TMYS expression which is indicative of their proliferative state, were found to be decreased in all brucellosis patients." (PMID 39135683, 2024). "A proliferative CD8+ T‐cell subset (CD8_Pro), characterized by high expression of MKI67 and TYMS, was obviously increased in acute brucellosis patients." (PMID 39135683, 2024). "Multiple activation markers, such as CD69, MKI67, CCL5, CTLA4, IFNG and GZMB, were found to be enriched in the NK cells of brucellosis patients, indicating the presence of an activated NK cell response as a distinctive feature for brucellosis patients, especially for those at the acute stage." (PMID 39135683, 2024).
liver failure (1 paper, 2025). A liver disease characterized by the liver losing or has lost all of its function. "However, proliferation markers Mki67 and Pcna remained downregulated, and ALT, a biomarker for liver failure and hepatocellular injury, remained elevated in CLP." (PMID 40904458, 2025).
mucinous lung adenocarcinoma (1 paper, 2022). "Using the K-M method, MKI67 and PCNA were confirmed as poor prognosis factors in stages I–III invasive non-mucinous lung adenocarcinoma." (PMID 36010686, 2022).
nephrotic syndrome (1 paper, 2025). A collection of symptoms that include severe edema, proteinuria, and hypoalbuminemia; it is indicative of renal dysfunction. "As such, the upregulation of Mki67 and Foxm1 may indicate the recovery process of tubular cells from micro-injury induced by nephrotic syndrome." (PMID 39666151, 2025). "mRNA expression of Foxm1 and Mki67 also significantly increased in this nephrotic syndrome model." (PMID 39666151, 2025).
Pulmonary hypoplasia (1 paper, 2022). "To determine whether differences in proliferation are a mechanism responsible for the diminished number of ECs and pulmonary hypoplasia, we examined Mki67 expression, noting no significant changes in the number of proliferating ECs at E18.5 by scRNA-seq." (PMID 36239312, 2022).
theileriosis (1 paper, 2023). "The presence of the MKI67 gene that codes for Ki-67 and is used as a marker for proliferation further corroborates that the Theileria parasite transforms the cell cycle machinery of the host, resulting in uncontrolled cell proliferation which is characteristic of theileriosis." (PMID 37761803, 2023).
tumor (17,756 papers, 1987 to 2026). "High MKI67+ tumor cell percentage was associated with better cancer-specific survival, an antitumorigenic immune microenvironment, downregulation of epithelial–mesenchymal transition, and upregulation of MYC signaling." (PMID 41201451, 2026). "Higher mRNA expression of MKI67 gene was associated with increased tumor size (p = 0.006), and increased stage (p = 0.003)." (PMID 40666735, 2025). "MKI67 expression, being a well‐established proliferation marker, was specifically chosen due to its association with highly proliferative tumours typically associated with worse prognosis." (PMID 39812592, 2025). "The LC1 subgroup was characterized by downregulation of genes associated with proliferation (i.e., FOXM1, MKI67) and lower G2M and E2F gene signatures, suggesting reduced rates of tumour growth." (PMID 41425537, 2025). "MKI67 is widely used in pathological evaluations and is tightly associated with tumor cell proliferation and growth." (PMID 41268575, 2025). "The gene name MKI67 encodes what is probably the best-known proliferation marker and is very frequently used in pathological studies in various tumor diseases." (PMID 40699665, 2025). "To study the potential clinical relevance of the MKI67+/HMGA1 regulatory network, we created a risk prediction model based on the major tumor cell subpopulation C2 MKI67+ TCs." (PMID 40842994, 2025). "The proliferation index Kiel 67 (Ki-67, encoded by MKI67 gene) protein is also an important biomarker for assessing tumor proliferating activity." (PMID 39275004, 2024). "The increased ILF2 levels were closely associated with the degree of tumor differentiation, clinical stage, and the proliferation marker MKI67." (PMID 39735599, 2024). "Ki-67 encoded by the MKI67 gene is a marker of cellular proliferation and is closely related to tumor malignancy." (PMID 38722833, 2024). "The 1° tumor had eight variants in MKI67, PRKN, PCLO, POLE, CDKN1C, IGSF3, and MED12 genes, which were also present in the brain and spine metastatic cell lines but not present in the parental cell line." (PMID 36900209, 2023). "in the ShortHER phase III trial found that HER2-enriched BC tumor with mutated PIK3CA had an upregulated expression of MKI67, MYBL2, ESR1, PDCD1 and other genes, but only MYBL2 and PDCD1 were related with a better DFS." (PMID 37313470, 2023). "Further subdivided into macrophage clusters were M1 macrophage, M2 macrophage, tumor-associated macrophage, MKI67+ progenitor cell, granulosa cell, and neutrophil." (PMID 37686305, 2023). "TM4SF1+, SOX4+, and MKI67+ tumor cells; CXCL12+ cancer-associated fibroblasts; CD4+ resident memory T cells; Treg; IgA+ plasma cells; and several myeloid subsets were enriched in stage IV CRC, most of which were associated with overall survival of patients." (PMID 37360193, 2023). "This set of cells also showed higher expression of MKI67 (encoding Ki-67) than other tumor cells (p-value < 2.2e−16, Wilcoxon test)." (PMID 38110427, 2023). "The genes with increased expression levels in ESRP1 high tumours include MKI67 (encoding the proliferation marker Mki67); the cell cycle regulator encoding genes CDK1, CCNA2, and CCNB2; and BIRC5 that inhibits apoptosis." (PMID 37752235, 2023). "We confirmed Cd68/Aif1-expressing tumour-associated microglia and Gfap/S100b-expressing astrocytes in close proximity to proliferating (MKI67-positive) tumour cells within the interface of drug-treated PDOX." (PMID 37127652, 2023). "Intriguingly, ectopic MYC in MET tumours increases expression of the Mki67 proliferation marker, and switches them into loss of Afp, Spp1, Gpc3, Epcam accompanied by an increase in Hgma1, Vim, and Hep-Par1 levels." (PMID 36433941, 2022). "A strong association between SF3B1 expression and key tumor -markers of development/progression (VEGFA/MKI67/EGFR/CDK4/PDGFRA) was found in GBM (CGGA- and Rembrandt-datasets), but not in the non-tumor samples (Rembrandt-dataset)." (PMID 35086552, 2022).
tumor (continued). "Cell proliferation–related genes, including Mki67, Cdk1, Plk1, and Ccnb1, were downregulated in tumor-infiltrating SENP7-deficient CD8+ T cells." (PMID 35143421, 2022). "The levels of Ki67 (encoded by gene MKI67) proliferation marker were also reduced in tumor tissues; this was seen most impressively for the combination therapy." (PMID 35681744, 2022). "B cells, MKI67+ T cells and dysfunctional T cells, interact with tumor-associated macrophages (TAMs), which are enriched by preoperative chemotherapy, through HLA-F-LILRB2 and HLA-DPB1-NRG1 pathways in the cell niche of primary tumors." (PMID 36465392, 2022). "To establish a direct link between GSTM1 and GSTM2 activity and tumor growth rate, we tested if their promoter methylation status is associated with the expression of the marker of proliferation Ki-67." (PMID 34871444, 2021). "As rapid proliferation represents a hallmark of tumor cells, a subcluster was distinguished by the high expression of Mki67." (PMID 34373258, 2021). "An elevated TOP2A expression is observed in many tumor tissues, and significantly associated with MKI67 expression as well as tumor aggressiveness and poor outcome." (PMID 33061942, 2020). "Higher levels of MKI67 expression in tumor tissue have been associated with a higher tumor grade and an earlier recurrence of disease." (PMID 30442201, 2018). "HER-2-enriched tumors have increased expression of proliferative genes, including BIRC5, CCND1, CCNE1, ORC6L, and MKi67, and are often associated with a more aggressive and highly proliferative tumor." (PMID 27896218, 2016). "Ki-67, which is encoded by MKI67, is a cell proliferation-related nuclear protein used for diagnosing tumor cell proliferation." (PMID 24467885, 2014). "MKI67 (Ki-67) gene products tightly associate with cellular proliferation and are often used to estimate tumor growth rates." (PMID 21958427, 2011). "Notably, the high expression of MKI67+ cell is likely associated with the high proliferation rate and invasiveness of tumor cells." (PMID 40666516, 2025). "In addition, there was a correlation between ESR1 mRNA levels and MKI67 expression, which is associated with tumor cellular proliferation." (PMID 40666735, 2025). "Moreover, tumor-associated (MKI67) and CAF-related (FAP, Fibronectin, COL1A1) genes were downregulated in the FAP/IL-15 CAR-T group compared to other groups." (PMID 41455698, 2025). "By contrast, luminal cluster 2 was enriched in a proliferative gene signature (Mki67, Ccnb2, Cdk1, Ccnb1 and Ccnd1), which may be associated with cycling progenitors fuelling tumour growth." (PMID 38238426, 2024). "Notably, SF3B3 expression demonstrated a positive correlation with MKI67, which encodes a proliferation marker for tumor cells." (PMID 38671459, 2024). "MKI67 encodes an important marker protein for tumor proliferation activity." (PMID 39590360, 2024). "Overall, these results demonstrated that the well‐established markers (i.e., ESR1, PGR, and MKI67) showed distinct spatial distributions and that the cells included in PNP spots (i.e., ESR1+ and/or MKI67+ cells) were potentially associated with oestrogen‐mediated tumour growth." (PMID 38282415, 2024). "CXCL9 is associated with tumor density and MKI67 expression." (PMID 39009698, 2024). "Furthermore, within the interface of the untreated PDOX, we observed proliferating (MKI67-positive) tumour cells in close proximity to Cd68-expressing tumour-associated microglia and Gfap-expressing astrocytes, similar to drug-treated PDOX." (PMID 37127652, 2023). "However, in the bulk of the untreated PDOX, while Cd68-expressing tumour-associated microglia were identified in close proximity to proliferating MKI67-positive tumour cells, Gfap-expressing astrocytes were notably absent." (PMID 37127652, 2023). "Using the TIMER platform, we found that TIPE1 expression in DLBCL was predicted to correlate with MKI67 expression, whether the association was adjusted by tumor purity (p < 0.05) or age (p < 0.05)." (PMID 36118167, 2022).
tumor (continued). "In addition, according to MEXPRESS-based analysis, MKI67 levels were related to sample type, simplified tumour stage, and fibrosis risk score." (PMID 34724892, 2021). "Biomarkers Mki67 and Bcl2 are also associated with tumour progression in the Mmtv-Pymt model." (PMID 34174867, 2021). "The expression of Ki67 (encoded by the MKI67 gene) is a marker for tumor cell proliferation." (PMID 32917965, 2020). "It is noteworthy that we observed only a weak-to-moderate association between DKC1 levels and actual markers of tumour proliferation, such as MKI67 and PCNA, suggesting that the increase in DKC1 expression is not simply a by-product of enhanced cell proliferation." (PMID 19755982, 2009). "Similarly, the gene MKI67, coding for the Ki-67 protein, is over-expressed during cell proliferation and both gene expression levels and protein expression in IHC have been shown to be linked with proliferation and more aggressive tumour behaviours." (PMID 39663527, 2024). "The results from these analyses suggest that the spatially distinct ST_2 group (including MKI67+ cells) had more impact than ST_0 on luminal cancer prognoses, and that luminal B tumours could be associated with a higher abundance of cells belonging to the ST_2 compartment." (PMID 38282415, 2024). "Furthermore, MKI67 was closely associated with the tumour immune microenvironment (TIME)." (PMID 34724892, 2021). "Expression of Mki67 was restricted to Subset 4, as well as other markers associated with cell proliferation, suggesting that this subset may represent a proliferating population of fibroblasts in the tumor microenvironment." (PMID 33298926, 2020). "Among the primary tumor samples, AKAP9, KDM2B, MAGED1, MKI67, PCLO, and TRAF1 mutations were identified." (PMID 41614915, 2026). "Densities and spatial localization of MKI67+ and MKI67− cytotoxic T cells and tumor proliferation rate were assessed via digital image analysis." (PMID 41201451, 2026). "Among the 95 primary tumor samples, AKAP9, KDM2B, MAGED1, MKI67, PCLO, and TRAF1 mutations were identified as single-occurrence events and were absent in the metastatic samples." (PMID 41614915, 2026). "To benchmark against tumor proliferation rate, we first evaluated ROC performance for MKI67+ tumor cell percentage and then compared CD8+ T-cell densities and G-cross function values for discriminating cancer-specific survival." (PMID 41201451, 2026). "In general, MKI67 was increased in most tumor types, with WNT tumors exhibiting the biggest increase." (PMID 41541220, 2026). "High MKI67+ tumor cell percentage positively correlated with antitumorigenic cell types such as CD3+ T cells, M1-like macrophages, and CD14+HLA–DR+ mature monocytic cells independent of MMR status and other factors (all P < 0.001)." (PMID 41201451, 2026). "Lastly, MKI67, UHRF1, and ESPL1 are associated with tumor proliferation and epigenetic regulation, with UHRF1 contributing to DNA methylation and DDR‐related transcriptional control." (PMID 40405535, 2025). "The cycling T cell population (cluster 11) displayed a strong signature of proliferation-associated genes including Mki67 and Top2a and included CD8+ and CD4+ cells and represented about 18% of the entire T cell population in tumours." (PMID 40473819, 2025). "The Tumor-4 subcluster had proliferating features and was marked by Mki67 and additional cell cycle genes, such as Kif23 and Ndrg1." (PMID 41332581, 2025). "Ki-67 protein is a nuclear antigen encoded by the MKI67 gene, and its elevated expression is frequently indicative of active tumor cell proliferation, increased malignancy, and poor prognosis." (PMID 41113459, 2025). "Analysis of tumor tissues revealed that MKI67+ cell percentages were reduced only in the combination group, while active caspase 3+ cell percentages were highest in the combination group." (PMID 39774471, 2025).
tumor (continued). "The spatial locations of tumour cells were determined by the expression of MYC, MYCN and PRDM6, along with other genes associated with proliferation (for example, MKI67)." (PMID 40335697, 2025). "report that high MKI67 has a good prognostic value for CRC, associated with low tumor stage and nodal status." (PMID 40070823, 2025). "As a reference for SNIP, the EGFR and MKI67 levels were significantly higher in tumor tissues than in paired normal tissues." (PMID 39744163, 2025). "Specifically, MKI67 expression showed a strong correlation with tumor grade, while ESR1 and ERBB2 also demonstrated significant differences between various grades and stages." (PMID 40948378, 2025). "In the Slingshot-constructed Lineage 1, C2 MKI67+ TCs exhibiting elevated CytoTRACE scores were situated at the terminal end, possibly indicating a distinct undifferentiated potential within the tumor differentiation trajectory." (PMID 40842994, 2025). "For example, the MKI67-Ki67 gene-protein pair shows higher correlation in tumour areas, which is consistent with its role as a marker of cell proliferation." (PMID 40735471, 2025). "High MKI67 expression is strongly correlated with aggressive tumor behavior, rapid growth, and poor prognosis." (PMID 40149331, 2025). "The TLT subtype, clustered by 45 genes involved in the cell cycle and DNA damage and repair, had higher expression of B-cell markers, BTK, BCR signaling genes, and MKI67, suggesting proliferative tumor cells as the cell resource." (PMID 39866884, 2025). "Subsequent staining of MKI67, a well-established marker of proliferation, revealed a marked reduction in MKI67 co-labeling within GFP+ tumor cells of the knockout group compared to the controls." (PMID 40428395, 2025). "The proliferating compartments within these subclones were also interspersed across the tumour tissue, observed by MKI67 expression." (PMID 40335697, 2025). "CDH1-E-Cad, KRT7/15-CK, MKI67-Ki67 are ST-SP pairs with stronger correlation in tumour regions of both samples." (PMID 40735471, 2025). "Spatial pseudotime analysis demonstrated these MBGS-low/Mki67-high nodules were insufficiently reprogrammed from zone 3 tumor to zone 1/2 hepatocytes, and transcriptional trajectory indicating tumoral origin." (PMID 40442146, 2025). "As anticipated, immunohistochemistry staining of PDX tumor tissues showed that treatment with si-circGRAMD4 resulted in reduced levels of MKI67/Ki67, LC3B, and NBR1 proteins, while increasing MHC-I protein levels." (PMID 40373256, 2025). "We conducted pertinent in vitro research centered on the HMGA1 gene to investigate its function as a principal transcription factor in C2 MKI67+ tumor cells." (PMID 40842994, 2025). "There was a moderate correlation between MKi67 mRNA ΔCt values and percent positive Ki67 staining tumor cells (r = 0.34, p < 0.001)." (PMID 40666735, 2025). "In the present study, four distinct tumor cell subsets, namely RPS4Y1+ tumor cells, LYZ+ tumor cells, CPE+ tumor cells, and MKI67+ tumor cells, were identified for the first time." (PMID 40230840, 2025). "For example, we identified regulatory CD4 T (Treg) cells and memory CD8 T (Temra) cells that highly express MKi67 in the new dataset, both of which showed a clear increase in tumor tissues." (PMID 39354287, 2025). "The combination groups exhibited a significant decrease in the MKI67-positive cells, the tumor vessel area, and the EPAS1 expression." (PMID 39477683, 2025). "We then verified the relationship between MKI67 expression and tumor-infiltrating immune cells via the TIMER algorithm." (PMID 40070823, 2025). "Confirming RECQL4’s independence from MKI67 as a prognostic factor would imply that RECQL4’s influence on patient prognosis extends beyond tumour proliferation rate." (PMID 39812592, 2025). "MKI67, a frequently employed marker for proliferation, can be used to examine the proliferative activity of tumor cells." (PMID 40978552, 2025).